QTGAL (queuosine-tRNA galactosyltransferase)
Description:
Glycosyltransferase that specifically catalyzes galactosylation of cytoplasmic tRNA(Tyr) modified with queuosine at position 34 (queuosine(34)). Galactosylates the cyclopentene hydroxyl group of queuosine(34) in tRNA(Tyr) to form galactosyl-queuosine(34). Mannosylation of queuosine(34) in tRNA(Tyr) is required to slow-down elongation at cognate codons UAC and suppress stop codon readthrough, thereby regulating protein translation.
Synonyms: BGnT-8; Beta3Gn-T8; Beta3GnTL1; B3GNT8; B3GNTL1; 3-Gn-T8; beta-1
Tractability: PROTAC: ubiquitination databases record sites on it.
Gene: Protein-coding gene on chromosome 17 (82,942,149 to 83,051,829, reverse strand). Ensembl gene ENSG00000175711.
Subcellular location: Cytoplasm
Subcellular location (Human Protein Atlas): Nucleoli; Nucleoli fibrillar center; Vesicles
Pathways (Reactome):
Metabolism of proteins: O-linked glycosylation of mucins
Gene Ontology:
Molecular function: tRNA-queuosine(34) galactosyltransferase activity; catalytic activity
Biological process: regulation of translation; tRNA modification; tRNA wobble guanine modification
Cellular component: cytoplasm
Genetic constraint (gnomAD): Loss-of-function variants: 55 observed, 50.12 expected, observed/expected ratio (o/e) 1.1, 90% interval 0.88 to 1.37. The upper end of that interval is the gene's LOEUF score, 1.37, which puts it in group 5 of 6, group 1 being the genes least tolerant of losing a copy. Missense variants: 465 observed, 447.83 expected, observed/expected ratio (o/e) 1.04, 90% interval 0.96 to 1.12. Synonymous variants: 193 observed, 173.65 expected, observed/expected ratio (o/e) 1.11, 90% interval 0.99 to 1.25.
Homologues: Orthologues: rat B3gntl1 (86% identical), mouse B3gntl1 (85% identical), guinea pig B3GNTL1 (84% identical), pig B3GNTL1 (84% identical), dog B3GNTL1 (83% identical), rabbit B3GNTL1 (80% identical), chimpanzee B3GNTL1 (79% identical), zebrafish b3gntl1 (65% identical), Caenorhabditis elegans F13G3.6 (41% identical).
Diseases named in the same sentence as QTGAL in open-access papers:
QTGAL is named in the same sentence as 8 diseases in open-access papers, as found by Europe PMC text mining. Sharing a sentence is not in itself a finding about the gene and the disease.
QTGAL shares sentences with these, for which no sentence is quoted: cancer (3 papers); lung carcinoma (2); acute myeloid leukemia (1); Alzheimer disease (1); colorectal cancer (1); colorectal tumors (1); tumor (1); type 1 diabetes (1).